STAT3 (signal transducer and activator of transcription 3)
Diseases named in the same sentence as STAT3 in open-access papers (continued):
Sharing a sentence is not in itself a finding about the gene and the disease.
prostate carcinoma (continued). "Taken together, these findings support evidence that CK induces apoptosis via the activation of miR193a-5p and inhibition of PD-L1 and STAT3 signaling in prostate cancer cells." (PMID 34440920, 2021). "We here demonstrate that the STAT3 inhibitor GPB730 enhances the antitumoral effect of anti-CTLA-4 treatment in a syngeneic prostate cancer mouse model." (PMID 33786638, 2021). "Androgen receptor knockdown in prostate cancer promotes cancer cell migration/invasion via CCL2- dependent STAT3 activation and EMT pathways." (PMID 33986252, 2021). "Yet, acetylation in K685 induces the transcriptional activity of STAT3 by increasing tyrosine phosphorylation and dimer stability in prostate cancer cell line (PC3)." (PMID 34642818, 2021). "Acacetin, a flavone present in various plants, inhibits constitutive and inducible STAT3 activation in STAT3-activated DU145 prostate cancer cells." (PMID 34684783, 2021). "Similar effect of CAR on STAT3 signaling, i.e., suppressed phosphorylation of STAT3 and blockade of nuclear translocation, has also been described in prostate cancer cells." (PMID 34073042, 2021). "Here the authors show that MSC-derived IL-28 induces prostate cancer cell apoptosis via IL-28Rα-STAT1 signalling, while acquired resistance to apoptosis is associated with a shift in IL-28Rα signalling via STAT1 to STAT3." (PMID 33526787, 2021). "Since it has been reported that CDK5 can interact with several important proteins in cancer progression, we also demonstrated that CDK5 has a direct protein-protein interaction with STAT3 in prostate cancer cell growth." (PMID 34207842, 2021). "MSC-selected apoptosis-resistant prostate cancer cells have elevated pSTAT3 and hyperactivation of STAT3 signaling occurs in many human cancers where it connotes poor prognosis and resistance to chemotherapy and radiation therapy." (PMID 33526787, 2021). "In the present study, we sought to investigate to enhance the efficacy of anti-CTLA-4 therapy against prostate cancer by the combination with STAT3 inhibition." (PMID 33786638, 2021). "Compared with silibinin alone, JAK1 inhibitors combined with silibinin also lead to complete reduction of STAT3 phosphorylation at Tyr705, activation of caspase, and apoptosis of prostate cancer cells." (PMID 34539403, 2021). "A previous study reported that excessive ROS production induces cancer apoptosis via inhibition of STAT3-mediated ER stress activation in prostate cancer and BC cells." (PMID 34638797, 2021). "We recently determined that HCA inhibits signal transducer and activator of transcription 3 (STAT3) signaling in prostate cancer cells." (PMID 33990689, 2021). "Our previous study showed that HCA inhibits the protein kinase activity of PKM2, which leads to the suppression of STAT3 phosphorylation in prostate cancer cells." (PMID 33990689, 2021). "To test the sensitivity of the F2 generated prostate cancer cell lines to STAT3 inhibition, we assessed the efficacy of the S3I-201 inhibitor in vivo." (PMID 33526787, 2021). "PIM-1 is regulated by STAT3 and is overexpressed in high-grade prostatic intraepithelial neoplasia and is overexpressed in 50% of human prostate cancers." (PMID 34439133, 2021). "We investigated the effect of combining anti-CTLA-4 treatment with the STAT3 inhibitor GPB730 on tumor growth in a prostate cancer mouse tumor model." (PMID 33786638, 2021). "IL-6 can activate an IL-6R/STAT3/miR-34a feedback loop in colorectal, breast and prostate cancer cells and it has been demonstrated that miR-34 repression is required for IL-6-induced EMT and invasion." (PMID 34361105, 2021). "The activation of the STAT3/Twist pathway in prostate cancer cells promotes epithelial–mesenchymal transition (EMT), allowing the cells to migrate." (PMID 34298624, 2021). "Here we have shown preferential STAT3 activity in MSC/IL-28-resistant prostate cancer that confers resistance to chemotherapies used to treat bone metastatic prostate cancer." (PMID 33526787, 2021).
prostate carcinoma (continued). "The miR-494-3p inhibitor increased tSTAT3 expression and increased the pSTAT3 levels, which confirmed that miR-494-3p regulated the progression of prostate cancer by targeting STAT3." (PMID 34094954, 2021). "In the present study, we investigated the possibility of enhancing the efficacy of anti-CTLA-4 therapy in a syngeneic prostate cancer mouse model by combining treatment with the STAT3 inhibitor GPB730." (PMID 33786638, 2021). "In the present study, the apoptosis mechanism of CK, a metabolite of processed ginseng (Black ginseng) saponins, was explored in prostate cancer cells in correlation with STAT3 and PD-L1 signaling." (PMID 34440920, 2021). "Selective inhibition of prostate cancer cell lines proliferation and mouse xenograft growth by inhibiting the expression of STAT3 target genes." (PMID 34630112, 2021). "Our study reveals that LINC00467 promotes prostate cancer progression via M2 macrophage polarization and the miR-494-3p/STAT3 axis." (PMID 34094954, 2021). "Activation of STAT3 signaling is essential for the metastatic progression of prostate cancer, and targeting the STAT3 pathway can be a potential therapeutic intervention for prostate cancer." (PMID 33919077, 2021). "We first evaluated the protein levels of PLZF and Tyr705 phosphorylation STAT3 (pY-STAT3) in 40 prostate cancer patients and 10 benign patient tissues, which were categorized according to Gleason scores (GS)." (PMID 32349303, 2020). "Altogether, these results validated that STAT3 acted as the primary response gene accounting for the promotion effect of CCL5 on prostate cancer cells." (PMID 32300100, 2020). "The inhibition of upstream tyrosine kinases has ledto downstream abrogation of STAT-3 signaling with antitumor effects in multiplepreclinical models, including prostate cancer." (PMID 32167126, 2020). "In this study, 456 people were enrolled and it was found that STAT3 induction has a reverse correlation with distant metastasis, but it can lead to the local progression of prostate cancer cells." (PMID 32545648, 2020). "It blocks the activation of the constitutive form of STAT3 in several tumor cell lines, such as U266 (multiple human myeloma), DU-145 (prostate cancer), SCC4 (squamous cell head-neck carcinoma)." (PMID 32283655, 2020). "STAT3 is an oncogene with functional activation closely related to the occurrence of prostate cancer." (PMID 32784629, 2020). "Collectively, these findings suggest that contribution of HOTAIR to prostatic cancer stemness is at least partly due to STAT3 activation." (PMID 32657763, 2020). "In the current study, we found that astaxanthin inhibits the proliferation of DU145 prostate cancer cells by reducing the level of STAT3." (PMID 32784629, 2020). "The introduction of STAT3 into prostate cancer (PC-3) cells greatly decreased the Warburg effect, as reflected by reduced lactate levels and elevated glucose-to-fatty-acid metabolism." (PMID 33003453, 2020). "In this study, we show that promyelocytic leukemia zinc finger (PLZF) has a putative tumor-suppressor function in prostate cancer by inhibiting phosphorylation of STAT3." (PMID 32349303, 2020). "In prostate cancer, silencing Hsp27 can decrease IL-6-dependent STAT3 phosphorylation, nuclear translocation, and STAT3 targeting of the Twist promoter, indicating that Hsp27 is required for IL-6-mediated EMT via regulation of STAT3/Twist signaling." (PMID 32315283, 2020). "Another clinical trial considered STAT3 as a factor involved in the migration of prostate cancer cells." (PMID 32545648, 2020). "This discovery matched the previous finding that the role of the STAT3/SHMT2/PKM2 loop was found to convert prostate cancer to a more aggressive phenotype." (PMID 33163414, 2020).
prostate carcinoma (continued). "STAT3 is activated in a wide variety of human tumors, including breast, lung, gastric, hepatocellular, colorectal, and prostate cancers." (PMID 33040485, 2020). "Human and murine prostate cancer models have exhibited varying effects of IL-6 and/or STAT3 on tumor cell growth." (PMID 35582225, 2020). "QPCR screening validated STAT3 as the most significant response gene in prostate cancer cells following CCL5 treatment." (PMID 32300100, 2020). "To confirm the key role of STAT3 in CCL5-induced promotion effect on prostate cancer, we further investigated the combined effect of CCL5 and STAT3 inhibitor." (PMID 32300100, 2020). "IL-6 acts through the Janus kinase (JAK)-signal transducer and activator of transcription (STAT) pathway which has been approached as anti-STAT3 therapeutics in several human cancers including prostate cancer." (PMID 35582225, 2020). "Increased occurrence of prostate cancer metastasis was also shown to be present in patients with co-deletion of STAT3 and CDKN2A." (PMID 32585812, 2020). "Research shows that hormone resistant prostate cancer cells have increased IL-6 expression and activated STAT3." (PMID 32326381, 2020). "Based on another investigation, nimbolide hindered STAT3 signaling and suppressed tumor formation in prostate cancer in vitro." (PMID 32545187, 2020). "PPAR gamma is a known suppressor of the interleukin 6 (IL-6)/STAT3 pathway, and prostate cancer progression positively correlates with STAT3 phosphorylation." (PMID 33182324, 2020). "IL-8 is primarily produced by prostate stromal cells and infiltrating macrophages to promote proliferation and inhibit apoptosis via the activation of the STAT3/AKT/NF-κB pathways in prostate cancer cells." (PMID 33076397, 2020). "We next elucidated if EVO can inhibit Src/STAT3 signal through blockage of c-Met signaling in prostate cancer cells." (PMID 32183146, 2020). "This research showed that in conjunction with silibinin, piceatannol (a JAK1 inhibitor) lessened STAT3 phosphorylation at Tyr705 and thus triggered caps, which induced the programmed cell death of prostate cancer cells." (PMID 32545187, 2020). "A similar approach was used on STAT3 in human prostate cancer cells, where the mutant STAT3-Y705F/S727E promoted survival, growth, and invasion." (PMID 32642677, 2020). "To validate this, we first determined the activation of STAT3 (Y705 tyrosine phosphorylation) in virus‐infected prostate cancer cells." (PMID 32100392, 2020). "The blocking of AR signaling can drive increased inflammation in prostate cancer cells by the induced expression of CCL2, promoting prostate cancer progression via activation of the STAT3 signaling pathway and recruitment of TAMs." (PMID 33076397, 2020). "It has been suggested that SHMT2 is downstream of signal transducer and activator of transcription 3 (STAT3) and plays a key role in the conversion of prostate cancer to a more aggressive phenotype." (PMID 33163414, 2020). "We examined PLZF, pY-STAT3, and STAT3 protein/mRNA levels by Western blotting/RT-PCR in prostate cancer cell lines." (PMID 32349303, 2020). "A study demonstrated that the anticancer effect of β-caryophyllene oxide was mediated through interfering with the activation of STAT3 in carcinoma cells, such as multiple myeloma cells (U266) and human prostate cancer cells (DU145)." (PMID 32545187, 2020). "Recently, it was shown to suppress the resistance of prostate cancer cells to enzalutamide, and its analogs SG-1709 and SG-1721 exhibited even greater effectiveness in blocking STAT3 signaling and inducing apoptosis." (PMID 32872659, 2020).
prostate carcinoma (continued). "In human leukemia and prostate cancer cells, cynaropicrin is able to induce glutathione depletion and result in S-glutathionylation of STAT3, leading to down-regulation of STAT3-dependent gene expression and chemosensitization of tumor cells to chemotherapy." (PMID 33505963, 2020). "It has been reported that STAT3-mediated Twist transcription is involved in IL-6/Hsp27-mediated EMT via STAT3 targeting of the Twist promoter in prostate cancer." (PMID 32315283, 2020). "Decreased phosphorylation of signal transducer and activator of transcription 3 (STAT3) in response to nelfinavir was observed in MM and prostate cancer." (PMID 33228205, 2020). "Silibinin blocked STAT3–DNA attachment, inhibited constitutively active STAT3 phosphorylation in prostate cancer cells, and induced caspase activation that contributed to cell death." (PMID 32545187, 2020). "STAT-3 has been shown to be involved in promoting integrin β6 transcription in oral squamous cell carcinoma and prostate cancer cells." (PMID 32855767, 2020). "Next, we sought to modulate STAT3 signalling in prostate cancer cells by pharmacological inhibition." (PMID 32100392, 2020). "Exclusion of the possible off‐target results by C188‐9, we stably knock‐downed STAT3 in both two prostate cancer cell lines with lentiviruses‐mediated shRNAs targeting STAT3." (PMID 32100392, 2020). "STAT3 is constitutively active in several cancers such as breast, lung, ovarian, colorectal, cervical, gastric, and prostate cancers, and head and neck squamous cell carcinoma." (PMID 33371351, 2020). "By suppressing Src and JAK2 phosphorylation, ursolic acid prevented the activation of STAT3 in prostate carcinoma cells." (PMID 32545187, 2020). "Recent studies explored the levels of total and activated Sta3 (phosphorylated Stat3, pStat3) during prostate cancer progression." (PMID 31366128, 2019). "We also provided evidences of the role of STAT3 and its PTMs as drivers in the progression of PCa in prostate cancer cells." (PMID 31500219, 2019). "A compound obtained from the leaves of G. biloba, ginkgetin, has demonstrated to inhibit both inducible and constitutively activated STAT3 and to block the nuclear translocation of p-STAT3 in DU145 prostate cancer cells." (PMID 31261861, 2019). "Hyperactive STAT3 and STAT5 are also implicated in various hematopoietic and solid malignancies, such as chronic and acute myeloid leukemia, melanoma or prostate cancer." (PMID 31817042, 2019). "While STAT3 activation has been extensively studied in prostate cancer development, its role in PCSCs has only recently been investigated." (PMID 31878027, 2019). "Over-activity of STAT3 in human cancers, including prostate cancer, is frequently the result of deregulation of upstream pathways with activation of protein tyrosine kinases associated with cytokine and growth factor receptors, like JAK family kinases." (PMID 31143708, 2019). "Our study was the first to demonstrate the interaction between CDK5 and STAT3 Ser-727 phosphorylation in prostate cancer cells and regulates cancer growth." (PMID 31395805, 2019). "With studies reporting niclosamide to inhibit NF-kB, mTOR and STAT3 pathway in uveal melanoma, cervical and prostate cancer respectively." (PMID 31383893, 2019). "Studies suggest that miR-17 overexpression leads to downregulation of STAT3 expression, which in turn, suppresses proliferation in human prostate cancer LNCaP cells." (PMID 31756185, 2019). "Prostate-cancer cells induce a change in macrophage phenotype from M1 into M2, through STAT3 activation." (PMID 31480382, 2019). "IL-6 expression in prostate tissues was increased in HFD-fed mice, as were the amounts of phosphorylated signal transducer and activator of transcription 3 (STAT3) in prostate cancer cells." (PMID 30736371, 2019).
prostate carcinoma (continued). "It is reported that SNHG12 accelerates the tumorigenesis of prostate cancer via sponging miR-133b and promotes the progression of the cervical cancer via modulating miR-125b/STAT3 axis." (PMID 31824846, 2019). "Increased STAT3 levels and higher Tyr705 and Ser727 phosphorylation are frequent in human prostate cancer both at early (androgen-dependent) and late (castration-resistant) stages of the disease." (PMID 31143708, 2019). "Recently, we reported that inhibition of 5-Lox downregulates expression and function of c-Myc in prostate cancer cells involving inhibition of Stat3-mediated transcription." (PMID 30728896, 2019). "Previous studies showed that cryptotanshinone has antibacterial activity, inhibits angiogenesis and inhibits STAT3 in prostate cancer." (PMID 32010087, 2019). "Recent studies with Stat3 small molecule inhibitors supported a high antitumor activity exerted both at the level of differentiated prostate cancer cells and of prostate cancer-initiating cells." (PMID 31366128, 2019). "STAT3 is an oncoprotein overexpressed in different types of tumors, including prostate cancer (PCa), and its activity is modulated by a variety of post-translational modifications (PTMs)." (PMID 31013746, 2019). "Different reports indicate that STAT3 is required for PD-L1 up-regulation in prostate cancer or osteosarcoma cell lines." (PMID 31697737, 2019). "Since CDK5 regulates both STAT3 and AR activation, it is important to further understand the detailed mechanism of this regulation in prostate cancer cells." (PMID 31395805, 2019). "Antisense oligonucleotide (ASO) targeting STAT3 mRNA has been a promising therapy in the treatment of androgen-independent prostate cancer currently being tested in clinical trials." (PMID 31771198, 2019). "UA also inhibits cell and tumor growth through suppressing NF-κB and STAT3 pathways in human prostate cancer DU-145 and LNCaP cells, and DU-145 xenograft mice, and induces apoptosis in human prostate cancer PC-3 cells." (PMID 31719837, 2019). "STAT3 is a point of convergence for numerous oncogenic signaling pathways and increased nuclear translocation and phosphorylation of STAT3 are related to prostate cancer growth, invasion, and metastasis." (PMID 30646518, 2019). "In prostate cancer bone metastases, which are largely poorly immunogenic, high tumor cell STAT3 phosphorylation, and IL-6R have been observed, as compared to lymph node and visceral metastases." (PMID 31842362, 2019). "EC-70124 blocked effectively both NF-κB and STAT3 activity in prostate cancer cells and particularly in tumor-sphere cells with constitutive activation of these pathways." (PMID 31143708, 2019). "The signal transducer and activator of transcription 3 (STAT3) pathway is observed to be constitutively activated in several malignancies including prostate cancer (PCa)." (PMID 30905090, 2019). "Activation of STAT3 can promote also immune-tolerance and chemo-resistance in prostate cancer through the secretion of immunosuppressive cytokines in the tumor microenvironment." (PMID 31143708, 2019). "Prostate cancer stem cells displayed a high constitutive Stat3 activity and were highly sensitive to the inhibitory effect of Stat3 inhibitors, even at low doses." (PMID 31366128, 2019). "Considering the significant role of STAT3 in prostate cancer and PCSCs, we analyzed the effect of MDA-9 on STAT3 in PCSCs." (PMID 31878027, 2019). "Activated STAT3 correlates with a higher Gleason score, pathological stage of prostate cancer, decreased survival, and shorter time to death as a consequence of biochemical relapse." (PMID 31878027, 2019). "Previous studies have shown that CT suppresses the proliferation of ovarian cancer cells and induced apoptosis of pancreatic as well as prostate cancer cells via the STAT3 signaling pathway." (PMID 31161238, 2019).